CHAC1 (ChaC glutathione specific gamma-glutamylcyclotransferase 1)
Diseases named in the same sentence as CHAC1 in open-access papers (continued):
Sharing a sentence is not in itself a finding about the gene and the disease.
endometriosis (1 paper, 2025). The growth of functional endometrial tissue in anatomic sites outside the uterine body.
Era (1 paper, 2025). "Consistent with Era treatment, ETEC infection decreased the expression of GPX4 and increased the mRNA levels of ChaC glutathione-specific gamma-glutamylcyclotransferase 1 (CHAC1) and solute carrier family 7 member 11 (SLC7A11)." (PMID 40867813, 2025).
glaucoma (1 paper, 2016). Increased pressure in the eyeball due to obstruction of the outflow of aqueous humor. "We thus suggest that Chac1 is involved in axonal injury-induced RGC death and is a promising, novel therapeutic target for neuroprotection in glaucoma treatment." (PMID 27353354, 2016).
injury (1 paper, 2024). Damage inflicted on the body as the direct or indirect result of an external force, with or without disruption of structural continuity. "A recent study showed that the upregulation of CHAC1 was positively correlated with ALT and AST levels in mice with acute liver injury." (PMID 39335604, 2024).
intracerebral hemorrhage (1 paper, 2025). A cerebrovascular disorder characterized by bleeding into one or both cerebral hemispheres including the basal ganglia and the cerebral cortex. "The regulation of CHAC1/BOTCH involves additional molecular players: during intracerebral hemorrhage, inhibition of CHAC1/BOTCH by the androgen receptor (AR) and Jumonji-domain containing protein-3 (JMJD3) led to elevated NOTCH1 levels and exacerbated neuroinflammation." (PMID 41488051, 2025).
ischemia reperfusion injury (1 paper, 2025). Adverse functional, metabolic, or structural changes in ischemic tissues resulting from the restoration of blood flow to the tissue (reperfusion), including swelling; hemorrhage; necrosis; and damage from free radicals. "Recent studies demonstrate that silencing CHAC1 in a murine intestinal ischemia-reperfusion injury model significantly inhibits ferroptosis and alleviates oxidative stress-induced tissue damage, further suggesting its involvement in modulating intestinal inflammation through ferroptosis regulation." (PMID 41312366, 2025).
liver cancer (1 paper, 2024). An epithelial or non-epithelial malignant neoplasm that arises from the liver. "In liver cancer, upregulation of CHAC1 expression is also closely related to disease progression and poor prognosis." (PMID 37948019, 2024). "In terms of mechanism, overexpression of MIA3 increases CHAC1 expression and promotes glutathione degradation in HCC to further promote the occurrence and development of liver cancer." (PMID 37948019, 2024).
lymph node metastasis (1 paper, 2024). "The univariate analysis revealed that sex (male), papillary type, lymph node metastasis, distant metastasis, TMN stage (III–IV), and high CHAC1 expression were associated with the survival rate; as such, they were included in the multivariate analysis." (PMID 39335604, 2024).
Mycobacterial infection (1 paper, 2021). "Mycobacterial infection can disrupt the ER to prompt ER stress, which can be induced by HIF-1α via activation of the ATF4, CHOP, and CHAC1 genes." (PMID 33535567, 2021).
periodontitis (1 paper, 2025). An acute or chronic inflammatory process that affects the tissues that surround and support the teeth. "In periodontitis, CHAC1 downregulation is observed in LPS-treated gingival fibroblasts, suggesting a potential protective role of CHAC1 loss in this specific inflammatory context." (PMID 41488051, 2025).
prostate adenocarcinoma (1 paper, 2021). "However, significant association between CHAC1 and neoantigens were noticed in BLCA (P = .00077), prostate adenocarcinoma (PRAD) (P = 7.1e‐06), LGG (P = .046), BRCA (P = 1.6e‐09) and READ (0.0011)." (PMID 33728749, 2021).
rhabdomyosarcoma (1 paper, 2023). A rare aggressive malignant mesenchymal neoplasm arising from skeletal muscle. "Of which, ChaC Glutathione Specific Gamma-Glutamylcyclotransferase 1 (Chac1) was identified as one of the most downregulated genes in combination treated rhabdomyosarcoma tumors compared to vehicle-treated tumors." (PMID 36816948, 2023).
rheumatoid arthritis (1 paper, 2025). A chronic, systemic autoimmune disorder characterized by inflammation in the synovial membranes and articular surfaces. "Primary screening found that ChaC1 overexpression mediated glutathione depletion dramatically enhanced the anti-cancer effect of auranofin (AUR), a gold (I)-containing compound approved by FDA since 1980’s to treat rheumatoid arthritis (RA)." (PMID 41249117, 2025).
ulcerative colitis (1 paper, 2025). An inflammatory bowel disease involving the mucosal surface of the large intestine and rectum. "CHAC1 may participate in the pathogenesis of ulcerative colitis via the miR-214-3p–STAT6 axis, while PML may be regulated by miRNAs with immunomodulatory functions, such as miR-146b-3p." (PMID 41312366, 2025).
urinary system tumors (1 paper, 2025). "This review aims to summarize the role of CHAC1 in urinary system tumors, providing strong evidence for its research as a new therapeutic target for urinary system tumors." (PMID 40860820, 2025).
urothelial carcinoma (1 paper, 2025). A malignant neoplasm derived from the transitional epithelium of the urinary tract (urinary bladder, ureter, urethra, or renal pelvis). "Notably, current evidence reveals no established link between CHAC1 and urothelial carcinoma pathogenesis." (PMID 40860820, 2025).
cancer (43 papers, 2012 to 2025). A tumor composed of atypical neoplastic, often pleomorphic cells that invade other tissues. "For instance, elevated CHAC1 mRNA levels are associated with increased recurrence risk in these cancers, underscoring its clinical relevance." (PMID 41488051, 2025). "Mechanistically, the increase in CHAC1 expression in cancer cells can be linked to the induction of ferroptosis through the ATF4 mediated UPR branch." (PMID 41488051, 2025). "uncovered a novel mechanism where cancer-associated fibroblasts (CAFs) in the TME regulate CHAC1 expression via exosomal delivery." (PMID 40860820, 2025). "CHAC1 activity is linked to cancer progression, influencing redox balance, cancer cell survival, proliferation, and therapy response." (PMID 39534397, 2024). "Although increased CHAC1 activity is associated with ferroptosis induction, we can see that upregulation of CHAC1 is commonly associated with poor prognosis in cancer patients." (PMID 39534397, 2024). "Increased expression of CHAC1 in cancer cells is linked to poor prognosis despite its role in degrading GSH and promoting ferroptosis." (PMID 39534397, 2024). "While several studies have reported a dual role for CHAC1 in cancer progression, studies depicting the association of CHAC2 in carcinogenesis are sparse." (PMID 36568153, 2022). "Similar phenomena have been reported in KIRC, such as CHAC1 expression was lower in cancer tissues than in normal samples, but was strongly associated with TNM stage and was a prognostic risk factor." (PMID 36405728, 2022). "Owing to the limitations of this pilot study, further studies should elucidate the role of CHAC1 and its transcript variants as potential biomarkers for identifying patients with high risk of cancer recurrence." (PMID 22108517, 2012). "High levels of CHAC1 are found in various cancers and are linked to poor prognosis." (PMID 39534397, 2024). "Modulating CHAC1 activity could enhance cancer cell susceptibility to ferroptosis, overcoming resistance to conventional therapies." (PMID 39534397, 2024). "CHAC1 is targeted by miR-432-5p derived from cancer-associated fibroblast (CAF) exosomes." (PMID 39534397, 2024). "Yet, CHAC1 also exhibits proapoptotic activity in some cancer models, highlighting its potential as a therapeutic target." (PMID 41488051, 2025). "This resistance is associated with impaired anti-tumor immunity and reduced efficacy of immunotherapy, highlighting CHAC1’s role as a vulnerability in cancer cells." (PMID 40860820, 2025). "Future investigations should focus on delineating the precise mechanisms of CHAC1 in ferroptosis regulation within different cancer contexts and exploring pharmacological approaches to modulate CHAC1 expression (e.g., activators) for therapeutic benefit." (PMID 40860820, 2025). "Functional assays revealed that CHAC1 upregulation significantly enhanced cancer cell death, as demonstrated through comprehensive phenotypic characterization." (PMID 40142049, 2025). "Understanding and targeting the CHAC1-ferroptosis axis holds significant potential for advancing cancer treatment." (PMID 40860820, 2025). "The pathological significance of CHAC1 and ferroptosis extends beyond cancer, having also been established in various neurological disorders." (PMID 41488051, 2025). "Specifically in oncology, CHAC1 shows varying expression patterns across different cancer types, where it can promote ferroptosis and increase oxidative damage." (PMID 41488051, 2025). "While the involvement of GSH metabolism in disease pathogenesis, including cancer, is well-documented, the specific regulatory mechanisms and consequences of CHAC1 activity across different tumor types and stages demand further elucidation." (PMID 40860820, 2025).
cancer (continued). "They showed that the CHAC1 gene is highly upregulated in HNSC cancer after treatment with nisin which was then followed by cell death." (PMID 41488051, 2025). "CHAC1’s contribution to tumor progression is markedly influenced by the cellular and tumor context, differing across various cancer types." (PMID 41488051, 2025). "Recently, CHAC1 was also discovered to be a key gene in ferroptosis and to augment cancer immunotherapy." (PMID 39893168, 2025). "Mechanistically, ChaC1 enhances ER stress sensitivity, promoting ferroptosis and necrotic cell death in various cancers." (PMID 40860820, 2025). "Collectively, these findings suggest that HG exerts an anti-cancer effect by promoting CHAC1-mediated ferroptosis." (PMID 40142049, 2025). "Studies show that inducing CHAC1 expression sensitizes cancer cells to chemotherapy and immunotherapy, indicating its potential in combination treatment strategies." (PMID 39534397, 2024). "By enhancing the expression of ChaC1, OP-B disrupts the cellular redox balance, promoting oxidative stress and leading to cancer cell death." (PMID 39534397, 2024). "In cancer cells, CHAC1 has been shown to influence the response to chemotherapy by modulating redox homeostasis and contributing to the induction of cell death pathways." (PMID 39534397, 2024). "This oncogenic behavior underscores the complexity of CHAC1’s function, where it can shift between promoting cell death in some cancers and supporting tumor survival in others." (PMID 39534397, 2024). "CHAC1 exhibits a complex, dual role in cancer, functioning as both an oncogene and a tumor suppressor, depending on the tumor context." (PMID 39534397, 2024). "The increased expression of CHAC1 in cancer cells leads to a depletion of intracellular GSH, contributing to oxidative stress and promoting cancer cell survival and proliferation." (PMID 39534397, 2024). "This detailed review of CHAC1 highlights its complex role in various cellular processes and its significant impact on disease pathology, particularly in cancer." (PMID 39534397, 2024). "By synthesizing current knowledge and recent findings, this review seeks to elucidate the critical contributions of ChaC1 to human diseases and cancers, highlighting its potential as a biomarker and therapeutic target." (PMID 39534397, 2024). "Understanding CHAC1 regulation and function across different cancer types can provide insights for potential therapies." (PMID 39534397, 2024). "By controlling these microRNAs, Loc100506691 effectively suppresses CHAC1 expression, thereby promoting cancer cell proliferation and affecting cell motility." (PMID 39534397, 2024). "In this context, CHAC1 acts as a tumor suppressor, weakening cancer cells’ defenses against stress and chemotherapeutic drugs." (PMID 39534397, 2024). "The duality of CHAC1’s role in cancer likely depends on the specific tumor microenvironment and interactions with other signaling pathways, such as the PI3K/AKT/mTOR or NRF2 pathways." (PMID 39534397, 2024). "Specifically, we observed that CHAC1 expression was significantly lower in patients with early stage cancer and increased as the malignancy advanced." (PMID 37313465, 2023). "Our transcriptomic analysis revealed the overexpression of the gene CHAC1 in both cancer cell lines, which show increased intracellular pools of pyroglutamic acid." (PMID 37299011, 2023). "Several studies have found the function of degrading GSH as CHAC1 in cancer; however, the role of CHAC2 in GSH degradation remains controversial in different cancers." (PMID 36899832, 2023). "We found CHAC1 expression is increased under multiple muscle wasting conditions in animal models, including fasting, cancer cachexia, and chemotherapy." (PMID 37014882, 2023). "In keeping with these results, the mRNA levels of several ER stress markers, such as CHOP, GRP75, CHAC1, and Sestrin2, were also upregulated by the EAAm treatment in cancer cell lines." (PMID 35367410, 2022).
cancer (continued). "We compared the expression of CHAC1 in different types of tumour samples and their corresponding normal samples using pan‐cancer sequencing data derived from TCGA database." (PMID 33728749, 2021). "Myc oncoprotein upregulates LYAR expression by activating its gene transcription, and the upregulation of LYAR, in turn, protects cancer cells against oxidative stress-mediated apoptosis through reducing CHAC1 gene expression." (PMID 32462040, 2020). "We found an increase of CHAC1 mRNA expression from benign neoplastic tissues through to grade III cancer tissues (P=0.014)." (PMID 22108517, 2012). "Our studies are the first to report CHAC1's new role in promoting cancer cell apoptosis under nisin treatment." (PMID 23342279, 2012). "Interestingly, another finding in the study is that prolonged methionine restriction reverses the depletion of GSH by inhibiting the expression of CHAC1 in cancer cells." (PMID 40430461, 2025). "Within this context, CHAC1 has emerged as a molecule exhibiting a dual role in cancer biology." (PMID 41488051, 2025). "However, the translational regulation of CHAC1 and its specific contributions to cancer metastasis and drug resistance warrant deeper investigation." (PMID 40860820, 2025). "Basal levels of CHAC1 are tightly suppressed in cancer cells." (PMID 39893168, 2025). "Mechanistically, intermittent methionine restriction can expedite ferroptosis in cancer cells by inducing the transcription and expression of cation transport regulator homolog 1 (CHAC1), which is a γ-glutamylcyclotransferase that specifically targets GSH into 5-OH and Cys-Gly." (PMID 40430461, 2025). "CHAC1’s function in cancer is complex and highly context-dependent." (PMID 41488051, 2025). "CHAC1 exhibits a complex “double-edged sword” role in different cancers." (PMID 40860820, 2025). "Although the exact role of CHAC1 in ferroptosis resistant cancer cells remains unclear, it presents an interesting target for cancer drug development as it plays a key role in multiple cellular processes associated with cancer." (PMID 41488051, 2025). "Furthermore, as expected, PI-mediated ChaC1 induction largely enhanced AUR’s anti-cancer activity in HCC cells." (PMID 41249117, 2025). "High-throughput screening from FDA-approved drug library using cell viability assay showed that auranofin (AUR) had a much more striking anti-cancer efficacy in ChaC1-overexpressed Huh7 cells than that in control cells, suggesting that AUR is one of the GSH-sensitive drugs." (PMID 41249117, 2025). "Additionally, CHAC1’s role in both promoting and inhibiting apoptosis and ferroptosis in a context-dependent manner across different diseases and cancers complicates its use as a therapeutic target." (PMID 39534397, 2024). "CHAC1 is crucial for maintaining redox balance and regulating cell death pathways in cancer." (PMID 39534397, 2024). "Prognostic and clinicopathological value of CHAC1 across different cancers." (PMID 39534397, 2024). "Thus, CHAC1’s upregulation enhances the survival and aggressiveness of cancer cells in the tumor microenvironment, leading to a poor prognosis." (PMID 39534397, 2024). "Clinically, modulating CHAC1 in combination with chemotherapy, radiotherapy, or immunotherapy could enhance treatment efficacy and overcome resistance in cancer patients." (PMID 39534397, 2024). "Many cancers exhibit CHAC1 upregulation, which correlates with poor prognosis." (PMID 39534397, 2024). "Furthermore, it was previously claimed that nisin negatively affected cancer cells via CHAC1 (ChaC Glutathione Specific Gamma-Glutamylcyclotransferase 1), a pro-apoptotic cation transport regulator and apoptotic mediator in carcinogenesis." (PMID 38672546, 2024).